IL6R-AS1 (IL6R antisense RNA 1)
Synonyms: RP11-350G8.5
Gene: Long non-coding RNA gene on chromosome 1 (154,402,328 to 154,406,564, reverse strand). Ensembl gene ENSG00000228013.
Diseases named in the same sentence as IL6R-AS1 in open-access papers:
IL6R-AS1 is named in the same sentence as 1 disease in open-access papers, as found by Europe PMC text mining. Sharing a sentence is not in itself a finding about the gene and the disease.
IL6R-AS1 shares sentences with these, for which no sentence is quoted: synovial sarcoma (1 paper).